DDIAS (DNA damage induced apoptosis suppressor)
Description:
May be an anti-apoptotic protein involved in DNA repair or cell survival.
Synonyms: C11orf82; NOXIN; FLJ38838; FLJ25416
Tractability: Antibody: the Human Protein Atlas places it where antibodies can reach. PROTAC: ubiquitination databases record sites on it.
Gene: Protein-coding gene on chromosome 11 (82,899,975 to 82,958,277, forward strand). Ensembl gene ENSG00000165490.
Subcellular location: Cytoplasm; Nucleus
Subcellular location (Human Protein Atlas): Cytosol; Plasma membrane
Gene Ontology:
Biological process: negative regulation of intrinsic apoptotic signaling pathway in response to DNA damage; regulation of DNA stability; negative regulation of apoptotic process
Cellular component: cytoplasm; nucleus
Genetic constraint (gnomAD): Loss-of-function variants: 5 observed, 9.4 expected, observed/expected ratio (o/e) 0.53, 90% interval 0.28 to 1.12. That is too few expected variants to judge how well the gene tolerates losing a copy. Missense variants: 957 observed, 1,100.4 expected, observed/expected ratio (o/e) 0.87, 90% interval 0.82 to 0.92. Synonymous variants: 330 observed, 386.8 expected, observed/expected ratio (o/e) 0.85, 90% interval 0.78 to 0.94.
Homologues: Orthologues: chimpanzee DDIAS (98% identical), macaque DDIAS (93% identical), pig DDIAS (69% identical), rabbit DDIAS (68% identical), dog DDIAS (66% identical), guinea pig DDIAS (58% identical), rat Ddias (50% identical), mouse Ddias (49% identical).
Diseases named in the same sentence as DDIAS in open-access papers:
DDIAS is named in the same sentence as 10 diseases in open-access papers, as found by Europe PMC text mining. Sharing a sentence is not in itself a finding about the gene and the disease. The quoted sentences say what the papers report.
lung carcinoma (6 papers, 2015 to 2023). "DDIAS promotes cellular proliferation and plays a significant role in advanced tumour metastasis in lung cancer, breast and liver cancer cells." (PMID 37121974, 2023). "DDIAS is highly expressed in several human cancers, including colorectal cancer, lung cancer, breast cancer and hepatocellular carcinoma (HCC), and stimulates cancer cell proliferation and cell cycle progression." (PMID 37121974, 2023). "DNA damage-induced apoptosis suppressor (DDIAS) is aberrantly expressed in human lung cancer, colon cancer, and hepatocellular carcinoma." (PMID 33859351, 2021). "DNA damage-induced apoptosis suppressor (DDIAS) promotes the progression of lung cancer and hepatocellular carcinoma through the regulation of multiple pathways." (PMID 33859351, 2021). "Consistent with our in vitro human lung cancer cell lines, DDIAS expression level was strongly correlated with STAT3 tyrosine phosphorylation." (PMID 31900385, 2020). "DNA damage-induced apoptosis suppressor (DDIAS) rescues lung cancer cells from apoptosis in response to DNA damage." (PMID 28079882, 2017). "DDIAS knockdown suppresses lung cancer cell invasion by decreasing β-catenin protein level on EGF exposure." (PMID 27660814, 2016). "DDIAS knockdown induced apoptosis in non-small cell lung carcinoma A549 cells in response to DNA damage, indicating DDIAS as a potential therapeutic target in lung cancer." (PMID 26740967, 2015). "Moreover, by promoting the expression of multiple target genes, including DDIAS, cyclin D1, IL-2, and IL-4, NFATc1 protects lung cancer cells against anticancer drug-induced death." (PMID 33859351, 2021). "Interestingly, we found that the expression of NFATc1 and DDIAS was elevated in H23 and H1703 cells, as well as in four gefitinib-resistant PDCs, but was downregulated in gefitinib-sensitive lung cancer cells, such as H358 and Calu-3 cells." (PMID 33859351, 2021). "DDIAS is highly expressed in lung cancers and is involved in cisplatin resistance." (PMID 27660814, 2016). "Therefore, DDIAS is suggested as a therapeutic target for lung cancer." (PMID 28079882, 2017). "Furthermore, DDIAS knockdown inhibited β-catenin accumulation and lung cancer cell invasion." (PMID 27660814, 2016). "Increasing evidence indicates that DNA damage-induced apoptosis suppressor (DDIAS) is an oncogenic protein that is highly expressed in a variety of cancers, including colorectal cancer, lung cancer, breast cancer, and hepatocellular carcinoma (HCC)." (PMID 37121974, 2023). "DNA damage-induced apoptosis suppressor (DDIAS), which is abundantly expressed in lung cancer and hepatocellular carcinoma (HCC), regulates the survival of cancer cells via multiple signaling pathways." (PMID 31900385, 2020). "We expect multiple, intertwined crosstalks and interactions between DDIAS/PTPRM and other STAT3 regulation system in lung cancer cells." (PMID 31900385, 2020).
breast carcinoma (2 papers, 2022 to 2023). "DDIAS expression is significantly linked with advanced tumor-node-metastasis stage in breast cancer and positive regional lymph node metastasis in NSCLC patients." (PMID 37121974, 2023). "In conclusion, the present results suggest that PSPC1 would facilitates hormone-dependent breast cancer proliferation by exhibiting RNA processing of ESR1 and SCFD2, the latter further contributes to anti-apoptotic or proliferative responses by modulating the expression of DDIAS and MYBL1." (PMID 35681031, 2022).
colorectal cancer (1 paper, 2023). A primary or metastatic malignant neoplasm that affects the colon or rectum. "However, DDIAS mRNA levels are significantly higher in lung, breast, and colorectal cancer tissues and cancer cell lines than in normal tissues or cells." (PMID 37121974, 2023).
COVID-19 (1 paper, 2024). A disease caused by infection with severe acute respiratory syndrome coronavirus 2. "Genome-wide significant associations with COVID-19 hospitalizations were found on chromosome 2 (within BAZ2B), chromosome 3 (within LZTFL1), chromosome 6 (within FOXP4), and chromosome 11 (within DDIAS)." (PMID 39361370, 2024). "Here, we present the findings of a GWAS meta-analysis in admixed Latin American (AMR) populations, comprising individuals from the SCOURGE Latin American cohort and the HGI studies, which allowed us to identify two novel severe COVID-19 loci, BAZ2B and DDIAS." (PMID 39361370, 2024).
cancer (6 papers, 2017 to 2023). A tumor composed of atypical neoplastic, often pleomorphic cells that invade other tissues. "DDIAS is clearly implicated in various oncogenic pathways and causes human cancer by linking multiple networks through its interactions with many nuclear and cytoplasmic binding partners." (PMID 37121974, 2023). "The DNA damage-induced apoptosis suppressor (DDIAS) protein is over-expressed in cancers, and plays key roles in tumour development, metastasis and drug resistance." (PMID 37121974, 2023). "DDIAS expression is induced by ultraviolet (UV) irradiation, and its level is highest in the S phase of the cell cycle in cancer and normal cells." (PMID 37121974, 2023). "The discovery of DDIAS as a novel therapeutic target and its role in human cancer biology is fascinating and noteworthy." (PMID 37121974, 2023). "This review focuses on the function of DDIAS and its regulatory proteins in human cancer as potential targets for cancer therapy, as well as the development and future prospects of DDIAS inhibitors." (PMID 37121974, 2023). "High expression of DDIAS in cancer contributes to malignancies mediated via a variety of mechanisms." (PMID 37121974, 2023). "Consistent with previous findings, we found that DGG-100629 induced JNK phosphorylation and that both transcriptional and pharmacological suppression of JNK reversed DGG-100629-induced DDIAS downregulation and restored cancer cell growth." (PMID 33859351, 2021). "Recent studies have shown that DDIAS is involved in tumorigenesis, metastasis, DNA repair and synthesis, and drug resistance and that it plays multiple roles with distinct binding partners in several human cancers." (PMID 37121974, 2023). "For the most part, DDIAS has been considered an oncogene in various cancers." (PMID 37121974, 2023). "DNA damage-induced apoptosis suppressor (DDIAS) was first discovered as a human homolog (hNoxin) of mouse noxin via genomic analysis of colorectal cancer patients and large-scale siRNA screening aimed at searching for cancer-related genes." (PMID 37121974, 2023). "DNA damage-induced apoptosis suppressor (DDIAS) regulates cancer cell survival." (PMID 31900385, 2020). "DDIAS positively regulates the protein levels of β-catenin and snail in HeLa and NSCLC cells treated with EGF, promoting cancer cell invasion." (PMID 37121974, 2023). "Therefore, DDIAS exhibits dual functions in inhibiting DISC formation, thereby suppressing TRAIL-mediated apoptosis of cancer cells." (PMID 37121974, 2023). "DDIAS is not a well-known gene to most cancer researchers even though it is noteworthy as a novel cancer therapeutic target." (PMID 37121974, 2023). "DDIAS is also involved in homologous recombination DNA repair and IL-6/STAT3 signaling activation, which may contribute to cancer progression." (PMID 35681031, 2022).
DDIAS also shares sentences with these, for which no sentence is quoted: hepatocellular carcinoma (4 papers); tumor (2); colon cancer (1); non-small cell lung carcinoma (1); osteosarcoma (1).